MYBBP1A (MYB binding protein 1a)
Description:
May activate or repress transcription via interactions with sequence specific DNA-binding proteins (By similarity). Repression may be mediated at least in part by histone deacetylase activity (HDAC activity) (By similarity). Acts as a corepressor and in concert with CRY1, represses the transcription of the core circadian clock component PER2 (By similarity). Preferentially binds to dimethylated histone H3 'Lys-9' (H3K9me2) on the PER2 promoter (By similarity). Has a role in rRNA biogenesis together with PWP1.
Synonyms: P160; PAP2; FLJ37886; Pol5
Tractability: PROTAC: UniProt records ubiquitination sites on it; ubiquitination databases record sites on it; its protein half-life has been measured.
Gene: Protein-coding gene on chromosome 17 (4,538,897 to 4,555,400, reverse strand). Ensembl gene ENSG00000132382.
Subcellular location: Cytoplasm; Nucleus; Nucleus, nucleolus
Subcellular location (Human Protein Atlas): Nucleoli; Vesicles
Pathways (Reactome):
Gene expression (Transcription): B-WICH complex positively regulates rRNA expression
Gene Ontology:
Molecular function: RNA binding; sequence-specific DNA binding; transcription corepressor activity; DNA binding; E-box binding
Biological process: cellular response to glucose starvation; osteoblast differentiation; positive regulation of anoikis; positive regulation of transcription by RNA polymerase III; regulation of G1 to G0 transition; chromatin remodeling; circadian regulation of gene expression; negative regulation of DNA-templated transcription; positive regulation of transcription by RNA polymerase I; positive regulation of transcription by RNA polymerase II; regulation of DNA-templated transcription
Cellular component: B-WICH complex; membrane; nucleolus; nucleus; cytoplasm; NLS-dependent protein nuclear import complex; nucleoplasm
Genetic constraint (gnomAD): Loss-of-function variants: 147 observed, 134.95 expected, observed/expected ratio (o/e) 1.09, 90% interval 0.95 to 1.25. The synonymous counts are far from expectation, so gnomAD's model fits this gene poorly and the ratio says little. Missense variants: 2,060 observed, 1,721.5 expected, observed/expected ratio (o/e) 1.2, 90% interval 1.15 to 1.24. Synonymous variants: 947 observed, 741 expected, observed/expected ratio (o/e) 1.28, 90% interval 1.21 to 1.35.
Homologues: Orthologues: chimpanzee MYBBP1A (99% identical), macaque MYBBP1A (91% identical), pig MYBBP1A (77% identical), dog MYBBP1A (76% identical), rabbit MYBBP1A (73% identical), guinea pig MYBBP1A (72% identical), mouse Mybbp1a (70% identical), rat Mybbp1a (70% identical), tropical clawed frog mybbp1a (43% identical), zebrafish mybbp1a (40% identical).
Diseases named in the same sentence as MYBBP1A in open-access papers:
MYBBP1A is named in the same sentence as 27 diseases in open-access papers, as found by Europe PMC text mining. Sharing a sentence is not in itself a finding about the gene and the disease. The quoted sentences say what the papers report.
colorectal cancer (7 papers, 2018 to 2025). A primary or metastatic malignant neoplasm that affects the colon or rectum.
head and neck squamous cell carcinoma (4 papers, 2012 to 2019). A squamous cell carcinoma that arises from any of the following anatomic sites: lip and oral cavity, nasal cavity, paranasal sinuses, pharynx, larynx, and salivary glands. "In this line, it has been detected an opposing function of MYBBP1A in proliferation and migration of head and neck squamous cell carcinoma cells (HNSCC)." (PMID 30781655, 2019). "An opposing function of MYBBP1A in proliferation and migration of head and neck squamous cell carcinoma cells (HNSCC) has also been detected." (PMID 30781655, 2019). "MYBBP1A is another gene in Merged module besides being a key regulator in tumor cell proliferation and migration e.g. head and neck squamous cell carcinoma." (PMID 23874428, 2013).
hepatocellular carcinoma (4 papers, 2021 to 2024). A malignant tumor that arises from hepatocytes. "In Huh-7 human hepatocellular carcinoma (HCC) cells, Mybbp1a promotes the methylation of CpG islands within the IGFBP5 gene by binding to DNA methyltransferase 1 (DNMT1), thereby blocking IGFBP5 transcription." (PMID 36093095, 2022).
breast carcinoma (3 papers, 2013 to 2021). "In this study, we show that MYBBP1A expression is associated with breast cancer tumorigenesis through an extensive analysis of the Oncomine database." (PMID 23388179, 2013). "To determine the role of MYBBP1A in cancer, we conducted an extensive analysis of the Oncomine database and IHC studies, and showed that MYBBP1A expression was associated with breast cancer tumorigenesis." (PMID 23388179, 2013). "However, the role of MYBBP1A in breast cancer prevention and the detailed mechanisms underlying these activities have not been determined." (PMID 23388179, 2013). "Furthermore, MYBBP1A expression has also been associated with breast cancer tumorigenesis." (PMID 30781655, 2019). "Of the 12 datasets, 11 contained gene chip profiles classified as normal or breast carcinoma tissues, which indicated that MYBBP1A mRNA levels were significantly lower in breast carcinomas than in normal tissues." (PMID 23388179, 2013). "Relationships between MYBBP1A expression levels and breast cancer progression were examined using patient microarray databases and tissue microarrays." (PMID 23388179, 2013). "In vivo and in vitro experiments using the breast cancer cell lines revealed that tumorigenesis, colony formation, and anoikis resistance were significantly enhanced by MYBBP1A knockdown." (PMID 23388179, 2013). "To investigate a possible relationship between MYBBP1A and breast cancer cell growth, we generated MCF-7 cells that had stably knocked down or overexpressed MYBBP1A." (PMID 23388179, 2013). "To examine the relationship between MYBBP1A expression and breast cancer progression, we examined the MYBBP1A expression profiles in breast carcinomas compared to those of normal tissue using the Oncomine database, which provides publicly available datasets of gene expression in cancer." (PMID 23388179, 2013). "MYBBP1A expression was significantly decreased in the breast cancer tumors." (PMID 23388179, 2013). "MYBBP1A expression was negatively correlated with breast cancer tumorigenesis." (PMID 23388179, 2013). "In this study, we revealed a function for the nucleolar protein MYBBP1A in breast cancer." (PMID 23388179, 2013). "The MYBBP1A protein levels were much lower in MCF-7 and ZR-75-1 cells, the cancer cell lines derived from human breast cancer cells, than in MCF-10A cells, a normal breast tissue cell line." (PMID 23388179, 2013). "Next, we used IHC to assess MYBBP1A expression in non-neoplastic and breast cancer tissues using a human breast cancer tissue microarray." (PMID 23388179, 2013).
pancreatitis (3 papers, 2017 to 2023). Inflammation of the pancreas. "The rs3809849 in the MYBBP1A gene was associated both with allergy and pancreatitis; the significant association with pancreatitis was replicated in the validation cohort." (PMID 28574850, 2017). "Interestingly, rs3809849 in the MYBBP1A gene was associated with allergy (p= 0.0006), pancreatitis (p=0.002), thrombosis (p=0.02), event-free survival (p=0.02) and overall survival (p=0.003)." (PMID 28574850, 2017). "Interestingly, rs3809849 in the MYBBP1A gene was associated with allergy, pancreatitis, thrombosis, event-free survival (EFS) and overall survival, while rs11556218 in IL16 gene and rs34708521 in SPEF2 gene were both associated with thrombosis and pancreatitis." (PMID 35582721, 2019). "The association of SNPs in MYBBP1A, SPEF2 and IL16 geneswith pancreatitis was replicated in the validation cohort (p ≤0.05) as well as in combined cohort (p=0.0003, p=0.008 and p=0.02, respectively)." (PMID 28574850, 2017). "Furthermore, the analysis in the context of a larger sample size provided by the combined cohort further supports the correlation between the SNPs in MYBBP1A, IL16 and SPEF2 with pancreatitis as the associations gained more significance in the pooled sample." (PMID 28574850, 2017).
renal cell carcinoma (3 papers, 2019 to 2020). "This suggests that, among the different subtypes of renal cell carcinoma, MYBBP1A loss is more frequent in chromophobe renal cell carcinoma, which could be a suitable subgroup when targeting the oxidative pathways as an alternative therapeutic approach." (PMID 31968688, 2020). "Finally, loss of MYBBP1A is observed in a significant percentage of patients with renal cell carcinoma, who show a metastatic tendency and poor prognosis, probably due to the increased stem phenotype caused by c-MYB activation." (PMID 30781655, 2019). "In conclusion, loss of MYBBP1A is observed in a significant percentage of patients with renal cell carcinoma, who may benefit from cancer therapies that target metabolic pathways." (PMID 31066170, 2019).
Allergy (2 papers, 2017 to 2024). An allergy is an immune response or reaction to substances that are usually not harmful. "The pivotal research marked the first demonstration of a link between the MYBBP1A gene and allergy risk." (PMID 39339172, 2024). "In a study carried out in 2017, an association between the MYBBP1A gene and the development of allergy related to ASNase was made." (PMID 39339172, 2024).
renal carcinoma (2 papers, 2019). A carcinoma arising from the epithelium of the renal parenchyma or the renal pelvis. "Here we show that MYBBP1A acts as a negative regulator of c-MYB, as loss of MYBBP1A leads to an increase of c-MYB activity in renal carcinoma cell lines." (PMID 30781655, 2019). "We identified that the downregulation of MYBBP1A increases tumorigenic properties, in vitro and in vivo, in renal carcinoma cell lines that express high levels of c-MYB exclusively." (PMID 30781655, 2019). "To explore the effect of MYBBP1A downregulation on the four renal carcinoma cell lines selected, we silenced MYBBP1A with a shRNA and achieved approximately 40–50% reduction of the protein." (PMID 31066170, 2019). "We believe that the activation of c-MYB by MYBBP1A downregulation confer selective advantages over other tumor cells, leading to clinically relevant renal carcinoma tumors." (PMID 30781655, 2019). "To explore the effect of MYBBP1A knock down on the 4 renal carcinoma cell lines, we used a shRNA against MYBBP1A and achieved approximately 40–50% reduction of the protein." (PMID 30781655, 2019). "MYBBP1A knock down in renal carcinoma cell lines results into an increase in c-MYB target genes expression, leading to an increase in the stem population." (PMID 30781655, 2019). "Perhaps the group of renal carcinoma with low MYBBP1A better counteracts this antioxidative pressure executed by the HIF factors on PGC1α and give some ccRCC with more mitochondrial activity that possibly alters its tumor phenotype." (PMID 31066170, 2019). "To explore the potential role of MYBBP1A as a tumor suppressor, we selected 4 different renal carcinoma-derived cell lines (786-O, ACHN, A498 and CaKi-1)." (PMID 30781655, 2019). "Finally, we have observed that approximately 10% of renal carcinomas have reduced MYBBP1A expression." (PMID 30781655, 2019). "Moreover, cells with MYBBP1A downregulation can be observed in clinically relevant renal carcinoma tumors, confirming their biological relevance." (PMID 31066170, 2019). "Furthermore, pVHL, which regulates MYBBP1A degradation, is frequently lost in renal cancer; therefore, we decided to use renal tumors and renal carcinoma cell lines as physiological models in our study." (PMID 30781655, 2019). "Therefore, we tested whether MYBBP1A also binds to c-MYB protein in our renal cancer cells by co-immunoprecipitation." (PMID 30781655, 2019). "We have also found that MYBBP1A knock down increases the expression of CD34, NANOG and CXCR4, which are target genes of c-MYB, exclusively in renal carcinoma cell lines that express high levels of c-MYB." (PMID 30781655, 2019). "After confirming that MYBBP1A was located in the nucleolus of renal cancer cells, as it has been described in other cell types, we observed co-localization of c-MYB and MYBBP1A in the nucleus, specifically nucleoli, of cells with high levels of c-MYB protein." (PMID 30781655, 2019). "We have observed the co-localization of MYBBP1A and c-MYB in the nucleolus of renal carcinoma cells and the co-immunoprecipitation of both proteins, which supports the hypothesis that MYBBP1A modulates c-MYB activity." (PMID 30781655, 2019). "A requirement of both pVHL isoforms 1 and 3 or other renal cancer-specific ubiquitin ligase, as suggested by the observation that MYBBP1A is ubiquitinated in the absence of VHL, could explain this discrepancy." (PMID 30781655, 2019).
clear cell carcinomas (1 paper, 2019). "Finally, to study the relevance of MYBBP1A loss in human tumors, we selected a cohort of 96 renal tumors, mostly clear cell carcinomas." (PMID 30781655, 2019).
clear cell renal cell carcinomas (1 paper, 2019). "To confirm this hypothesis, we analyzed the expression of MYBBP1A in different types of tumors on cBioportal database and found that clear cell renal cell carcinomas (ccRCC) showed a set of tumors with the lowest expression of MYBBP1A." (PMID 30781655, 2019).
colon cancer (1 paper, 2026). "Furthermore, cProSite analysis revealed that, among the top positive co-regulations, phosphorylations at MYBBP1A_S1241, RSL1D1_S392, and ADD3_S679 were consistently co-regulated with CIT_S440 in colon cancer samples compared to adjacent normal samples." (PMID 41601480, 2026).
lung adenocarcinoma (1 paper, 2013). A carcinoma that arises from the lung and is characterized by the presence of malignant glandular epithelial cells. "We have discovered ATP6V1C1, MYBBP1A, MACF1 and MYO10 upregulation in lung adenocarcinoma and accordingly, it is concluded that these genes have an important role in lung adenocarcinoma metastasis and we have reported all the mentioned genes for the first time in lung adenocarcinoma." (PMID 23874428, 2013).
Obesity (1 paper, 2021). Accumulation of substantial excess body fat.
osteosarcoma (1 paper, 2022). A usually aggressive malignant bone-forming mesenchymal neoplasm, predominantly affecting adolescents and young adults.
pancreas tumors (1 paper, 2020). "By analyzing MYBBP1A mRNA levels in paired samples of normal and tumoral tissue, MYBBP1A expression levels have been found to be reduced mainly in the kidney, liver and pancreas tumors." (PMID 31968688, 2020).
renal oncocytomas (1 paper, 2019). "In the KORT database, around 32% of samples showed low MYBBP1A expression and high expression of TCA genes, all of these samples being chRCCs or renal oncocytomas." (PMID 31066170, 2019). "In the KORT database, around 32% of samples showed low MYBBP1A expression, high PGC1α expression, and high expression of c‐MYB target genes, all of these samples being chRCCs or renal oncocytomas." (PMID 31066170, 2019).